FLCN (folliculin)
Diseases named in the same sentence as FLCN in open-access papers (continued):
Sharing a sentence is not in itself a finding about the gene and the disease.
Birt-Hogg-Dube syndrome (continued). "Definite diagnosis of Birt-Hogg-Dubé Syndrome requires genetic testing for folliculin mutations." (PMID 30326848, 2018). "Birt-Hogg-Dubé syndrome is a genetic syndrome caused by mutations in the FLCN gene." (PMID 29548312, 2018). "Furthermore, the metastasis appears to be linked to BHD syndrome since it showed loss-of-heterozygosity in the FLCN gene." (PMID 28499369, 2017). "Although TS and BHD are clearly unique syndromes, recent articles demonstrated that both FLCN protein (mutated in BHD syndrome) and tuberous sclerosis complex (TSC) protein (mutated in TS syndrome) lead to activation of mammalian target of rapamycin complex 1 (mTORC1) of the mTOR pathway." (PMID 25610687, 2014). "Rare mutations in the folliculin gene (FLCN) have been implicated in two genetic syndromes with shared pulmonary manifestations of spontaneous pneumothorax and lung cyst formation: Birt-Hogg-Dubé syndrome (BHD, MIM 135150) and familial spontaneous pneumothorax (FSP, MIM 173600)." (PMID 19116017, 2008). "Since carcinogenesis in BHD syndrome is assumed to occur according to the Knudson’s hypothesis sequencing findings most likely represented loss-of-heterozygosity with deletion of the second FLCN allele in tumor tissue." (PMID 28499369, 2017). "Birt-Hogg-Dubé syndrome (BHDS) is an autosomal dominant cancer predisposition syndrome, caused by pathogenic variants in FLCN, characterized by benign fibrofolliculomas, pulmonary cysts, pneumothorax, and increased risk for kidney tumors." (PMID 41193855, 2026). "The FLCN gene variant, in combination with the results of NGS, led to the diagnosis of Birt-Hogg-Dubé syndrome (BHD)." (PMID 39867882, 2024). "The FLCN gene, located on chromosome 17p11.2, was identified as a tumor suppressor gene in 2002 and is responsible for BHD syndrome." (PMID 39300538, 2024). "Birt-Hogg-Dubé syndrome (BHDS) is a rare, autosomal dominant condition, which arises from mutations in the folliculin (FLCN) gene." (PMID 37273290, 2023). "The definitive diagnosis of BHD syndrome heavily relies on a genetic evaluation of the major BHD syndrome-causing gene, that is, FLCN gene." (PMID 37417625, 2023). "Birt-Hogg-Dubé syndrome (BHD) is a hereditary disorder, identified in only 200 families worldwide, and has been identified to be an autosomal dominant mutation in the FLCN gene." (PMID 36895521, 2023). "As for FLCN c.1432 + 1G > A, also known as IVS12 + 1G > A, independent studies have discovered this classical splicing site variant in BHD syndrome patients; our study is the first to report its occurrence in Asian populations." (PMID 37417625, 2023). "Birt-Hogg-Dube syndrome (BHDS) (MIM: 135150) is a rare autosomal dominant disorder with variable penetrance, caused by pathogenic variants in the FLCN gene." (PMID 35176117, 2022). "Birt-Hogg-Dubé syndrome (BHD) is a dominantly inherited kidney cancer syndrome caused by mono-allelic germline loss-of-function mutations of the essential and conserved Folliculin (FLCN) gene." (PMID 33459596, 2021). "Birt-Hogg-Dubé syndrome (BHD) is a rare inherited autosomal dominant disorder first described in 1977, and caused by mutations in the tumour suppressor gene FLCN coding for folliculin." (PMID 32448321, 2020). "A locus for BHD syndrome was mapped to chromosome 17p11.2 by linkage analysis in BHD families, and subsequently germline mutations in the FLCN gene were identified." (PMID 33137092, 2020). "Birt-Hogg-Dubé syndrome (BHD, OMIM #315150) is an autosomal dominant condition caused by germline mutations in the FLCN gene encoding folliculin and is characterized by fibrofolliculomas, lung cysts, spontaneous pneumothorax and renal cell carcinoma (RCC)." (PMID 30845233, 2019). "Birt-Hogg-Dubé syndrome (BHDS), a rare, inherited autosomal dominant genodermatosis caused by a germline mutation in the folliculin (FLCN) gene, was first reported in 1975 and 1977." (PMID 29764481, 2018).
Birt-Hogg-Dube syndrome (continued). "Folliculin (FLCN) is a tumor suppressor whose function is lost in Birt-Hogg-Dubé syndrome (BHD), a disorder characterized by renal cancer of multiple histological types including clear cell carcinoma, cutaneous fibrofolliculoma, and pneumothorax." (PMID 23922894, 2013). "This convergence in the functions of VHL and FLCN is of special interest considering the fact that clear cell carcinoma can be part of the multihistological type of renal cancer that occurs in BHD syndrome." (PMID 23922894, 2013). "Germline mutations in a tumor suppressor gene FLCN lead to development of fibrofolliculomas, lung cysts and renal cell carcinoma (RCC) in Birt-Hogg-Dubé syndrome." (PMID 21209915, 2010). "Mutations in the folliculin (FLCN) gene have been implicated in Birt-Hogg-Dubé syndrome (BHD, OMIM135150), an autosomal dominant genodermatosis which predisposes for multiple fibrofolliculomas, renal carcinoma, lung cysts and SP." (PMID 20932317, 2010). "Masaya’s team reaffirmed that mutations in FLCN and its interacting partner FNIP1, involved in Birt-Hogg-Dubé syndrome, may play a role in energy and nutrient sensing through the AMPK and mTOR signaling pathways." (PMID 40143966, 2025). "Notably, germ-line mutations in other members of the folliculin complex, FLCN gene, are associated with Birt-Hogg-Dube syndrome, which is characterized by fibrofolliculomas, renal tumors, lung cysts, and pneumothorax." (PMID 36316722, 2022). "In BHD syndrome, the mutation in the FLCN gene that encodes for folliculin is at 17p11.2." (PMID 25610687, 2014). "The FLCN gene is responsible for the hereditary human tumor disease called Birt-Hogg-Dube syndrome (BHD)." (PMID 24763318, 2014). "Conversely, adenovirus mediated wild-type FLCN or FLCN/FNIP1 expression suppressed GPNMB mRNA expression more than 2 fold, but mutant FLCN (c.1285dupC, most frequent mutation in BHD syndrome), mutant FLCN/FNIP1 or FNIP1 alone did not suppress GPNMB expression in UOK257 cells." (PMID 21209915, 2010). "Interestingly, this locus contains another kidney tumor-suppressor gene, folliculin (FLCN), whose activity is lost in the genetic autosomal-dominant disorder, Birt-Hogg-Dubé syndrome (BHD)." (PMID 23922894, 2013). "Importantly, FLCN c.1432 + 1G > A has been reported in patients with BHD syndrome and colorectal cancer, whereas it has not been recorded in any general population databases." (PMID 37417625, 2023). "Birt-Hogg-Dubé syndrome is excluded by not detecting any aberration in the folliculin gene locus." (PMID 29067220, 2017). "This study will shed light on the understanding of FLCN/FNIP1/FNIP2/AMPK function and the downstream target genes and signaling pathways that are important in tumorigenesis, providing insight into therapeutic targets for treatment of renal tumors that develop in BHD syndrome and translocation RCC." (PMID 21209915, 2010).
pneumothorax (62 papers, 2008 to 2026). Abnormal presence of air in the pleural cavity. "Recently, a 28.4–37.3% lifetime risk of pneumothorax in FLCN-mutation carriers was reported to age 65 years." (PMID 40770455, 2025). "This syndrome is caused by pathogenic variants of the folliculin gene (FLCN gene) encoding folliculin, which predisposes to pneumothorax through dysregulated matrix metalloproteinase activity, leading to elastic fiber degradation in the pulmonary parenchyma." (PMID 41305765, 2025). "The diagnosis of BHDS is confirmed by multiple cutaneousfindings, pulmonary cysts and spontaneous pneumothorax history,renal tumors, or any combination of these with familial andidentification of a germline variant in FLCN by DNA sequencing." (PMID 40145825, 2025). "Patients with FLCN mutations in exons 9 and 12 had a higher frequency of pneumothorax compared to patients with mutations in other exons." (PMID 40336059, 2025). "Large intragenic deletion of exons 1–3 in FLCN was identified as a local aggregation phenomenon in Feidong County, China, and was associated with a significantly higher risk of pneumothorax compared to those with point mutations." (PMID 37170274, 2023). "Using univariate analysis, chest pain, history of pneumothorax, and radiological features (number, maximal diameter, and shape of lung cysts) were significantly associated with FLCN mutations." (PMID 37370942, 2023). "Association between FLCN variants and pulmonary symptoms is well established, indicating that carriers have an up to 32-fold risk for spontaneous pneumothorax compared to general population, together with a high predisposition to develop lung cysts." (PMID 35176117, 2022). "Spontaneous pneumothorax, mutation, renal cell carcinoma, family, folliculin, BHD gene, cancer, fibrofolliculoma, pulmonary cyst, diagnosis, management, and tumor suppressor gene were keywords with high occurrence frequency." (PMID 35479937, 2022). "The prevalence of FLCN mutations was 94% (15/16), 43% (15/35), and 54% (14/26) according to presentations of family history of pneumothorax, cystic lung disease, and family screening, respectively." (PMID 35578266, 2022). "In 2008, the first 10 families with spontaneous pneumothorax and positive FLCN mutations in the Chinese population were described by a research team at Nanjing University." (PMID 34001170, 2021). "We found that 50.9% of reported individuals with FLCN variants had suffered at least one pneumothorax, which is considerably higher than the 30% typically quoted." (PMID 34267338, 2021). "FLCN variants are associated with the development of basal pulmonary cysts that are prone to rupture causing pneumothorax." (PMID 34267338, 2021). "Since a research team from Nanjing University firstly explored the FLCN gene mutations on patients with spontaneous pneumothorax history in 2008, there has been more than 20 families with BHDS in China up to 2017 according to the BHD foundation statistics." (PMID 34001170, 2021). "Significantly increased pneumothorax risks were observed for mutations c.1300G > C (59%) and c.250-2A > G (77%) compared with FLCN hotspot mutation c.1285dup (37% risk)." (PMID 34001170, 2021). "Since the existence of ‘pneumothorax-only’ FLCN variants would have important consequences for screening protocols, we examined these in more detail." (PMID 34267338, 2021). "There was rather high incidence of pneumothorax associate with FLCN hotspot mutation c.1285dup (60% risk) in this cohort." (PMID 34001170, 2021). "It has however been suggested that some FLCN variants only cause pneumothorax, which would make surveillance unnecessary in certain cases." (PMID 34267338, 2021). "We recommend that all individuals found to carry a pathogenic FLCN variant be offered lifelong surveillance for renal cancer, since pneumothorax-only FLCN variants are likely to be rare." (PMID 34267338, 2021).
pneumothorax (continued). "Birt–Hogg–Dubé syndrome (BHDS, MIM #135150), caused by germline mutations of FLCN gene, is a rare autosomal dominant inherited disorder characterized by skin fibrofolliculomas, renal cancer, pulmonary cysts and spontaneous pneumothorax." (PMID 33927747, 2021). "The BHD patient had a germline FLCN heterozygous mutation (c.779 + 1G > T), repeated episodes of pneumothorax, and cutaneous basal cell carcinomas." (PMID 34337482, 2020). "Some researchers have reported that FLCN mutations in exon 9 and 12 are associated with a higher number of pulmonary cysts, a larger cyst diameter, and more episodes of pneumothorax." (PMID 33240319, 2020). "Mutations in exons 9 and 12 of FLCN have been reported to be associated with a higher number of cysts, larger cysts, and a higher incidence of pneumothorax." (PMID 31625278, 2019). "The aim of this study is to present a Turkish family in which 13 members from three generations of the same family developed recurrent isolated spontaneous pneumothorax with a novel mutation in the FLCN." (PMID 31625278, 2019). "Some mutations have been reported in different exons of the FLCN in cases of isolated familial spontaneous pneumothorax." (PMID 31625278, 2019). "Birt–Hogg–Dubé (BHD) syndrome, a hereditary renal cancer syndrome caused by mutations in the folliculin (FLCN) gene, is characterized by the presence of fibrofolliculomas, pulmonary cysts, spontaneous pneumothorax, and renal cell carcinoma (RCC)." (PMID 28069055, 2017). "To date, approximately 169 variants of FLCN have been reported in BHD or isolated pneumothorax and renal carcinoma patients." (PMID 28785590, 2017). "We demonstrated that the full spectrum of genes associated with pneumothorax including FLCN gene mutations can be identified simultaneously in multiplexed sequence data." (PMID 27229674, 2016). "Birt–Hogg–Dubé syndrome (BHDS) is an autosomal dominant inherited disorder caused by germline mutations in the FLCN gene, and characterized by skin fibrofolliculomas, multiple lung cysts, spontaneous pneumothorax, and renal neoplasms." (PMID 27905298, 2016). "BHD is an autosomal dominant condition caused by germline mutations in the folliculin (FLCN) gene, clinically characterized by skin fibrofolliculomas, pulmonary cysts (recurrent) spontaneous pneumothorax and an increased risk of renal cell cancer." (PMID 27652079, 2016). "Birt-Hogg-Dubé (BHD) syndrome is a cancer disorder caused by a pathogenic FLCN mutation characterized by fibrofolliculomas, lung cysts, pneumothorax, benign renal cyst, and renal cell carcinoma (RCC)." (PMID 24772173, 2014). "Of the 115 FLCN mutation carriers 28 had a history of pneumothorax, frequently recurrent and bilateral." (PMID 22146830, 2011). "Birt–Hogg–Dubé (BHD) syndrome is an autosomal dominant condition caused by germline FLCN mutations, and characterised by fibrofolliculomas, pneumothorax and renal cancer." (PMID 22146830, 2011). "Among the 115 FLCN mutation carriers, 28 (24%) had a history of pneumothorax, recurrent in eight patients." (PMID 22146830, 2011). "For example, in one extended family with FSP, all 13 folliculin mutation carriers had cysts on chest CT, though only 5 had a history of pneumothorax." (PMID 19116017, 2008). "Loss-of-function folliculin mutations have also been described in pedigrees with familial spontaneous pneumothorax." (PMID 19116017, 2008). "The subgroup analysis focusing on diagnostic methods specifically compared the incidence of spontaneous pneumothorax in patients with BHD syndrome based on whether FLCN mutation testing was used or other diagnostic criteria were applied." (PMID 40336059, 2025). "Studies have confirmed that when the FLCN gene is mutated, macrophages and fibroblasts secrete a large number of inflammatory factors, which eventually cause the destruction of lung elastic fibers, and lead to pneumothorax." (PMID 41305765, 2025).
pneumothorax (continued). "Specific FLCN mutations found in Asian populations might predispose these individuals to a higher risk of developing pulmonary cysts and spontaneous pneumothorax." (PMID 40336059, 2025). "Reports of a constitutional pathogenic FLCN variant in kindreds with a “familial pneumothorax only” phenotype led to suggestions that BHD syndrome and isolated familial pneumothorax might be allelic." (PMID 39085584, 2024). "It was concluded that all individuals with a constitutional FLCN PV, even in the presence of a personal and family history of a pneumothorax only phenotype, should be considered to be at risk of renal tumours and offered appropriate renal surveillance (R10, R11)." (PMID 39085584, 2024). "Via standard bioinformatics analysis and variant annotation (reference human genome GRCh37/hg19), we determined that the recurrent pneumothorax is most likely caused by a heterozygous splicing mutation in the FLCN gene (c.1432 + 1G > A; rs755959303), which was further confirmed by Sanger sequencing." (PMID 37417625, 2023). "Most individuals with BHD who had pulmonary cysts (six of seven) and spontaneous pneumothorax (four of five) had disease-causing FLCN variants in exons 11 and 12, consistent with previous correlations between pulmonary features and pathogenic variants in exon 9 and greater." (PMID 34604083, 2021). "In some cases, it has been suggested that specific FLCN variants could result in a pneumothorax-only phenotype." (PMID 34267338, 2021). "Although it is known that such FLCN variants increase the risk of pneumothorax by up to 50-fold, the true proportion of pneumothoraces in BHDS remains unclear." (PMID 34267338, 2021). "It has been observed in BHDS patients that FLCN mutations in exon 9 are associated with an increased number of lung cysts and exon 9 and 12 mutations are correlated with more episodes of spontaneous pneumothorax." (PMID 33240319, 2020). "The present identification of two mutations not only further supports the important role of tumor suppressor FLCN in BHD and primary spontaneous pneumothorax, but also expands the spectrum of FLCN mutations and will provide insight into genetic diagnosis and counseling of families with BHD." (PMID 28785590, 2017). "Birt-Hogg-Dubé (BHD; ORPHA122) syndrome is an autosomal dominant disorder caused by loss-of-function mutations in the folliculin (FLCN) gene and characterized by skin fibro-folliculomas, multiple lung cysts lined by fibrous band (in up to 90% of cases), spontaneous pneumothorax, and renal cancer." (PMID 23075428, 2012). "Folliculin has been hypothesized to play a role in emphysema, and rare folliculin mutations have been associated with cyst formation and spontaneous pneumothorax." (PMID 19116017, 2008). "In addition to location, pathologically abnormal epithelial/mesenchymal interactions induced by FLCN mutation may weaken the extracellular matrix of the visceral pleura, leading to pneumothorax." (PMID 37221571, 2023). "Of the 194 pathogenic FLCN variants, 76 could be defined as ‘pneumothorax-only’." (PMID 34267338, 2021). "BHDS is a rare inherited autosomal dominant disorder caused by germline mutations in the tumor suppressor gene FLCN that predisposes affected individuals to develop benign skin tumors (fibrofolliculomas), renal neoplasms, and pulmonary cysts with a risk of spontaneous pneumothorax." (PMID 34001170, 2021). "In addition, FLCN mutation analysis should be considered for patients who have familial cystic lung disease, familial pneumothorax, familial renal cancer, or any combination of spontaneous pneumothorax and kidney cancer." (PMID 22146830, 2011). "Many experiments have shown that, among these, the FLCN gene in BHD syndrome is the most closely related gene in familial spontaneous pneumothorax." (PMID 41305765, 2025).